AREG (amphiregulin)
Diseases named in the same sentence as AREG in open-access papers (continued):
Sharing a sentence is not in itself a finding about the gene and the disease.
infection (40 papers, 2011 to 2025). The state of being infected such as from the introduction of a foreign agent such as serum, vaccine, antigenic substance or organism. "In the present study we report that infection with N. gonorrhoeae causes altered amphiregulin processing and release in human epithelial cells." (PMID 21298020, 2011). "Interestingly, prior immunization with 2W1S peptide was associated with elevated spontaneous release of amphiregulin by lung cells isolated 3 days post-infection following a 72 hour culture period." (PMID 34237106, 2021). "Studies have divulged the importance of amphiregulin in intestinal tissue regeneration and repair after chemical or infection-induced damage." (PMID 38376154, 2024). "Accumulating evidence has established a complex role for AREG as a modulator of tissue homeostasis, resistance to infection, tissue remodeling, and resolution of inflammation." (PMID 36797300, 2023). "Parasitic infection of colitic mice resulted in upregulation of mucosal AREG, EGF, FGF-2, and IGFBP-3 in the intestine of the host and better adaptation (infectivity)." (PMID 36836678, 2023). "For instance, we detected an upregulation of the Cardiotrophin-like cytokine factor 1 (Clcf1) and Amphiregulin (Areg) in the Vγ6+ cells during infection, which is predicted to engage with their cognate receptors Cntfr and Egfr, respectively." (PMID 37644007, 2023). "It was shown before, that Th2 cells express AREG, which was required for protective immunity after TM infection." (PMID 36430676, 2022). "After resolution of infection, ILC2s also help to repair the damaged tissues via the production of amphiregulin (AREG)." (PMID 36430676, 2022). "The role of intestinal ILC2 during pathogen infection is to promote intestinal epithelium integrity via IL-5, IL-13, and amphiregulin, which leads goblet hyperplasia and mucus production." (PMID 30770814, 2019). "We find less AREG and TGF-α in the supernatant of ADAM17-depleted cells, corroborated by a reduction of the infection rate after treatment with AREG and TGF-α neutralizing antibodies." (PMID 31107240, 2019). "Previous data of our group suggest that pro-AREG is increasingly expressed on neonatal monocytes, leading to remarkably higher soluble AREG levels after infection compared to monocytes from adults." (PMID 32082070, 2019). "AREG is constitutively expressed during development and in homeostatic states but increases dramatically in response to inflammation or infection." (PMID 30012205, 2018). "By influencing monocyte function and survival during infection, AREG potentially plays a role in shaping the response of other immune cells like T lymphocytes." (PMID 30524196, 2018). "IAV infection of Areg knock-out (Areg−/−) mice eliminated sex differences in IAV pathogenesis, with a more significant role for AREG in infection of male compared to female mice." (PMID 30012205, 2018). "Another mechanism to promote tissue repair following infection is the activity of amphiregulin, which acts on the epithelium to induce cell proliferation much like IL-22." (PMID 29988424, 2018). "In the present study we investigated amphiregulin in prolonged infection by N. gonorrhoeae in the human cervical epithelial cell line Me-180." (PMID 21298020, 2011). "An upregulation of the transcription of amphiregulin mRNA was detected after infection compared to untreated cells and normalized to housekeeping gene GAPDH." (PMID 21298020, 2011). "The upregulation peaked after 6 hours of infection with more than 20-fold increase in amphiregulin mRNA levels." (PMID 21298020, 2011). "After 24 hours of infection, the subcellular localization of the bioactive domain of amphiregulin was changed from the cytoplasm to the nuclear membrane." (PMID 21298020, 2011).
infection (continued). "The protein changes its subcellular distribution and is also alternatively cleaved at the plasma membrane, which results in augmented release of an infection-specific 36 kDa amphiregulin product from the surface of human cervical epithelial cells." (PMID 21298020, 2011). "Upon infection, the majority of the full-length 50 kDa pro-amphiregulin is rather cleaved immediately into a 36 kDa product, exclusively localized to the cytoplasm and nuclear fraction as determined by western blot." (PMID 21298020, 2011). "An increased release would therefore lead to more amphiregulin bound to the surface of the Me-180 cells that in turn leads to a stimulatory response in the cell to upregulate amphiregulin at 6 hours post infection." (PMID 21298020, 2011). "Host cell transcriptional upregulation of amphiregulin occurs in infections of Shigella flexneri, EHEC, and Helicobacter pylori." (PMID 21298020, 2011). "Upon infection, amphiregulin is shuttled within the Me-180 cell in a pattern different from uninfected cells." (PMID 21298020, 2011). "Since mRNA of amphiregulin was upregulated several fold during infection with N. gonorrhoeae, we then analyzed the protein expression, cleavage and release upon infection." (PMID 21298020, 2011). "This additional amphiregulin cleavage product is bigger in mass, indicating that amphiregulin processing induced by the infection is different from regular amphiregulin cleavage in uninfected control." (PMID 21298020, 2011). "In the context of inflammation and infection, ILC2s may also produce amphiregulin (Areg), a member of the epidermal growth factor family of signaling factors, which facilitates the restoration of tissue integrity and homeostasis." (PMID 32079296, 2020). "In the muscle, Tregs participate to tissue repair through the secretion of amphiregulin, which facilitates the regeneration of muscle satellite cells; similarly, amphiregulin production by Treg cells helps contain the damage to lung tissue following infection." (PMID 31956323, 2019). "Moreover, infection analyses showed that infection rates were significantly reduced when AREG or TGF-α neutralizing antibodies were added to the cells 1 hr before HPV16 PsVs addition." (PMID 31107240, 2019). "Our experimental setting is based on E. coli as model organism, and even though we additionally showed that stimulation with AREG reduces monocyte PICD upon infection with S. agalactiae and C. albicans, the role of AREG in these settings needs to be more thoroughly explored." (PMID 30524196, 2018). "In this study, AREG transcript abundance was significantly enhanced by infection only in the resistant breed, suggesting that this gene may play an important role in the development of host resistance." (PMID 27197554, 2016). "More importantly, the quantitative real-time PCR data supported that viable SC19 infection of hBMEC could stimulate the upregulation of AREG, EREG, and HB-EGF, while the heat-inactivated SC19 was unable to upregulate these ligands." (PMID 27756321, 2016). "We demonstrate that upon infection, a massive upregulation of amphiregulin mRNA is seen." (PMID 21298020, 2011). "However, HEC-1-B cells released very low levels of the alternatively processed form of amphiregulin after 6 hours of infection with MS11 P+." (PMID 21298020, 2011). "Although we detected Amphiregulin expression by several types of innate cells, the induction of Amphiregulin expression was most pronounced in alveolar macrophages, which were also one of the most frequent types of leukocytes appearing in the lungs over the first three days of infection." (PMID 30770250, 2019). "Collectively, the research done with both IL-22 and amphiregulin provides examples of the importance of host tolerance in maintaining barrier function in the lung and returning to homeostasis in order to promote survival following infection independent from resistance." (PMID 29988424, 2018).
infection (continued). "Module 2 focused on epithelial barrier function and growth factor signaling, identified EREG, FGFR2, and MET as central hubs, alongside AREG and HBEGF, which support epithelial repair and regeneration after infection-induced damage." (PMID 40634947, 2025). "The Epidermal Growth Factor Receptor (EGFR) and its ligand, amphiregulin (AREG) are critical for epithelial cell proliferation but their important role in inflammation and infection is increasingly described." (PMID 41063987, 2025). "Progesterone increased IL-6, TGF-β, and regulatory Th17 cells and upregulated the epidermal growth factor amphiregulin (AREG), facilitating lung recovery from the infection." (PMID 40558589, 2025). "Adding ADAM17 cleavage products such as AREG, TGF-α, and HB-EGF to the supernatant of serum-starved or ADAM17-depleted cells increases ERK1/2 phosphorylation and infection." (PMID 31107240, 2019). "Our data suggest ADAM17-mediated release of GFs such as AREG, TGF-α or HB-EGF, known activators of ERK signaling as an important step in infection with oncogenic papillomaviruses." (PMID 31107240, 2019). "In conclusion, our data demonstrate that the innate-like effector function of Th2 cells at the site of infection is controlled by EGFR and AREG expression." (PMID 29045902, 2017). "Our quantitative PCR data showed that three ligands, HB-EGF, AREG and EREG, displayed significant up-regulation at 60 min after infection with strain RS218, while the transcriptional levels of EGF, BTC and TGFα remained unchanged during the infection." (PMID 27711202, 2016). "AREG expression has been reported in epithelial cell layers and various immune cells, including dendritic cells, neutrophiles, and CD4+ T cells, and is constitutively upregulated in response to inflammation or infection." (PMID 38229736, 2024). "The higher expression levels of AREG and the increased persistence of ILC9 cells in vivo could thus play important roles in lung tissue repair after infection or allergen exposure." (PMID 38597952, 2024). "They constitute a dominant ILC population in lung and have been reported to promote the repair of lung epithelial cells to restore the epithelial integrity via production of amphiregulin (AREG) and thus increase the resistance of host to infection and decrease the pathogen burden in lungs." (PMID 34621268, 2021). "Since we demonstrated that both ERK1/2 and Akt phosphorylations are induced by infection-mediated activation of EGFR, we wanted to investigate whether these signaling events mediate phosphorylation of the protein BAD through AREG signaling." (PMID 32082070, 2019). "Moreover, the induction of EGFR and amphiregulin occurred at later time points than that for EGR1, i.e., at 4–6 h post infection." (PMID 28180113, 2017). "The increased expression of amphiregulin with LANCL2 activation may be a key component in the reduction of epithelial necrosis and lung damage during infection." (PMID 28270815, 2017). "The mRNA expression of RORα and amphiregulin was not changed after 1 or 7 days of H pylori–SS1 infection." (PMID 28210674, 2015). "We show that the infection by N. gonorrhoeae MS11 P+ immediately enhances the transcription of amphiregulin in ME-180 cells and HEC-1-B cells, but not in VK2/E6E7 cells." (PMID 21298020, 2011). "Even though, this is not in agreement with previous findings where LOS expressing N. meningitidis did not increase the transcription of amphiregulin after 6 hours of infection." (PMID 21298020, 2011). "During the resolution phase of infection event, IL-33 acts on residential ST2-expressing group 2 innate lymphoid cells (ILC2s) as well as regulatory T (Treg) cells to restore airway tissue homeostasis, mediated at least partly by amphiregulin (AREG)-dependent repair of virus-damaged epithelium." (PMID 38704386, 2024). "Additionally, we also sorted PD-1+Treg and PD-1neg Treg cells from tonsils and examined the expression of secondary markers such as IFN-γ and AREG with and without infection." (PMID 34446704, 2021).
infection (continued). "Prior to infection, no sex differences in Areg mRNA or AREG protein were observed." (PMID 30012205, 2018). "The 28 kDa band represents the regular release of amphiregulin and did not increase upon infection." (PMID 21298020, 2011). "Though these amphiregulin-producing T cells do not correlate with enhanced Hulk clearance, these data may indicate that 2W1S immunization can improve lung tissue repair later following infection." (PMID 34237106, 2021). "Furthermore, P4-treatment did not activate markers of ILC2s, including IL-13 and IL-33 production, or increase numbers of Tregs in the lungs during infection, suggesting that the induction of AREG in response to P4 may not be occurring in these immune cell populations." (PMID 27631986, 2016). "The results showed that the triple deletion mutant was able to induce significant up-regulation of AREG and EREG after 60 min, while there was no up-regulation of HB-EGF, as well as EGF, BTC, and TGFα, after infection with the triple deletion mutant." (PMID 27711202, 2016).
adenocarcinoma (6 papers, 2009 to 2019). A common cancer characterized by the presence of malignant glandular cells. "The activation of AREG by AGR2 has been shown to be dependent on the Hippo pathway effector protein YAP1 in human adenocarcinoma cell lines." (PMID 31434729, 2019). "The human adenocarcinoma-associated gene, AGR2 (anterior gradient 2), induces expression of amphiregulin through activation of YAP1 in PC." (PMID 27738325, 2016). "Increased expression of ErbB receptors or ligands, such as transforming growth factor-α (TGFα), amphiregulin (AREG), neuregulin-1 (NRG1), and cripto-1 (TDGF-1), are associated with mammary hyperplasia and adenocarcinoma development." (PMID 23383347, 2013). "RT-PCR confirmed that amphiregulin (Areg), epiregulin (Ereg), fetuin beta (Fetub), claudin 2 (Cldn2), hepatic nuclear factor 4, alpha (Hnf4α), glutathione S-transferase, alpha 4 (Gsta4) and forkhead box A3 (Foxa3) were up-regulated in adenocarcinoma." (PMID 19812696, 2009). "Previous work established that adenocarcinoma cell lines from the lung and esophagus are dependent on AGR2, YAP1, and AREG to maintain the transformed phenotype." (PMID 27764193, 2016).
bacterial infection (5 papers, 2011 to 2025). "After understanding amphiregulin in uninfected control Me-180 cells, we then investigated amphiregulin during bacterial infection in three different cell lines." (PMID 21298020, 2011). "Early bacterial infection induces amphiregulin mRNA upregulation, alternate processing and cleavage, subcellular localization and release." (PMID 21298020, 2011).
cardiovascular diseases (3 papers, 2022 to 2025). "AREG is a member of epidermal growth factor family, which plays a key role in cardiovascular diseases." (PMID 35996142, 2022). "Specifically, Amphiregulin is involved in the pathogenesis of various cardiovascular diseases." (PMID 35732465, 2022). "The role of Amphiregulin/EGFR in cardiovascular diseases has been reported." (PMID 35732465, 2022).
immune dysfunction (3 papers, 2024 to 2025). "In addition, AREG’s function in promoting chemoresistance and PD-L1 immune dysfunction provides strong rationale for combinatorial approaches with HGSOC standard of care chemotherapy and PD-1 based immunotherapy." (PMID 38831884, 2024).
kidney disease (3 papers, 2025). "This significant unmet clinical need has driven research into novel therapeutic targets, among which AREG has emerged as a promising candidate due to its central role in mediating inflammatory and fibrotic responses in kidney disease." (PMID 40725192, 2025). "Recent clinical studies have established AREG as a potential biomarker for kidney disease progression, with elevated levels detected in kidney biopsy tissues, serum, and urine samples from patients with CKD, AKI, and DKD." (PMID 40725192, 2025).
benign tumours (1 paper, 2018). "Important upstream regulators in our study, unique to benign tumours were AREG, TLR2, TGF1B, HGF, MAP3K1." (PMID 30517191, 2018).
CNS tumors (1 paper, 2018). "Well-characterized TEAD targets in non-CNS tumors include CTGF, Cyr61, MYC, CCNE1, AREG, and EGFR44,54,55." (PMID 30275445, 2018).
infectious disease (1 paper, 2016). A disorder directly resulting from the presence and activity of a microbial, viral, or parasitic agent in humans. "We have demonstrated that AREG, which is a significant factor that induces tissue repair and recovery from infectious diseases, is regulated by P4 during both lethal and sublethal IAV infection." (PMID 27631986, 2016).
AREG also shares sentences with these, for which no sentence is quoted: serous ovarian cancer (3 papers); cholangiocarcinoma (2); endometriosis (2); esophageal squamous cell carcinoma (2); experimental autoimmune encephalomyelitis (2); idiopathic inflammatory myopathy (2); keratoconus (2); lupus nephritis (2); renal cell carcinoma (2); systemic lupus erythematosus (2); thoracic aortic aneurysm (2); (SARS-CoV) infection (1); acute myeloid leukemia (1); acute respiratory distress syndrome (1); alcohol (1); Alzheimer disease (1); aortic aneurysm (1); Arrhythmia (1); bacterial pneumonia (1); bacterial sepsis (1); benign epithelial tumors (1); brain cancer (1); breast (1); campomelic dysplasia (1); cataract (1); Cholestatic liver disease (1); chronic gastritis (1); chronic kidney disease (1); Cirrhosis (1); colon (1).
A further 48 diseases each share a sentence with AREG in 1 paper.